PTH (parathyroid hormone)
Diseases named in the same sentence as PTH in open-access papers (continued):
Sharing a sentence is not in itself a finding about the gene and the disease.
secondary hyperparathyroidism (continued). "Finally, in cases of severe and refractory secondary hyperparathyroidism (persistent serum PTH > 1000 pg/mL) in which treatment with vitamin D sterols is ineffective or contraindicated due to persistent hypercalcemia and hyperphosphatemia, subtotal parathyroidectomy may be considered." (PMID 38672265, 2024). "In fact, secondary hyperparathyroidism is known to develop from stage 2 CKD in humans, and a four-fold increase in parathyroid hormone (PTH) level can be observed when end-stage kidney disease develops." (PMID 37989901, 2024). "As basal PTH levels can be modified by s-IP, MHD patients are prone to be at high s-IP levels, resulting in increased PTH secretion and possible secondary hyperparathyroidism." (PMID 36788486, 2023). "Secondary hyperparathyroidism (SHPT), characterized by elevated parathyroid hormone (PTH) levels secondary to disruption in calcium and vitamin D homeostasis, is a normal physiologic response that occurs with progressive kidney disease." (PMID 38707996, 2023). "Despite similar parathyroid hormone levels, both vitamin D and calcimimetic use decreased in the HHD group, reflecting better control of secondary hyperparathyroidism." (PMID 38106580, 2023). "A frequent comorbidity of CKD is secondary hyperparathyroidism (SHPT), exemplified by high serum parathyroid hormone (PTH) levels." (PMID 37834950, 2023). "A common complication among CKD patients is secondary hyperparathyroidism (SHPT), a complex alteration in bone and mineral metabolism characterized by excessive parathyroid hormone (PTH) production and parathyroid gland hyperplasia." (PMID 36480088, 2023). "This view adds to the effects of parathyroid hormone in CKD patients and the classical treatment of secondary hyperparathyroidism." (PMID 37342799, 2023). "Patients with secondary hyperparathyroidism (SHPT) show a left-shift in their PTH-Ca2+ curve, indicating that higher levels of serum Ca2+ are needed to activate CaR-mediated inhibition of PTH secretion." (PMID 37064904, 2023). "Variations in tumor characteristics and surgical approaches were observed, with studies indicating a higher incidence of PTC in females, varying tumor sizes, and differences in PTH levels between PHPT and secondary hyperparathyroidism (SHPT) cases." (PMID 38202152, 2023). "Low serum parathyroid hormone (PTH) and secondary hyperparathyroidism (SHPT) are very common in patients undergoing hemodialysis." (PMID 35634511, 2022). "Our analysis also revealed that PTH is elevated in both TIO and XLH but that a small fraction of these people have been diagnosed with secondary hyperparathyroidism." (PMID 35229062, 2022). "Indeed, the authors suggest that increased PTH concentrations in the setting of normocalcemia, normal kidney function and 25OHD above 20 ng/ml are more likely to indicate primary hyperparathyroidism, while secondary hyperparathyroidism should be suspected for 25OHD concentrations <20 ng/ml." (PMID 36187131, 2022). "In the progression of secondary hyperparathyroidism (SHPT), the expression of CaSR in the parathyroid gland decreases and thus limits the regulation of PTH secretion based on calcium levels." (PMID 35140213, 2022). "In the progression of secondary hyperparathyroidism (SHPT), expression of calcium-sensing receptors (CaSR) in the parathyroid gland decreases, which leads to persistent hypersecretion of PTH." (PMID 35140213, 2022). "D receptor activators (VDRA) can prevent parathyroid hormone (PTH) secretion and secondary hyperparathyroidism (SHPT) in CKD." (PMID 36558475, 2022). "Therefore, although obesity per se may be associated with higher serum PTH levels in CKD patients, severe secondary hyperparathyroidism seems to be inversely correlated to body adiposity status and implicated in the pathogenesis of advanced CKD-related cachexia." (PMID 34422722, 2021).
secondary hyperparathyroidism (continued). "Secondary hyperparathyroidism (SHPT), characterized by elevated serum parathyroid hormone (PTH) levels, is a common mineral bone disorder in patients with chronic kidney disease (CKD)." (PMID 33481922, 2021). "In the current study, we observed secondary hyperparathyroidism due to VDI, which was significantly higher as compared to patients with normal PTH levels in spite of inadequate VD levels (p ≤ 0.0001)." (PMID 34249532, 2021). "Secondary hyperparathyroidism (SHPT), a common and serious complication of end-stage renal disease (ESRD), is characterized by increased parathyroid hormone (PTH), calcium and phosphate levels, with substantial mortality." (PMID 32631272, 2020). "Secondary hyperparathyroidism (SHPT), which is characterized by serum parathyroid hormone (PTH) elevation, is a common mineral metabolism abnormality in patients with chronic kidney disease (CKD)." (PMID 32343734, 2020). "The particular form of secondary hyperparathyroidism known as SNHPT is characterized by low serum 25-hydroxy vitamin D levels, high PTH levels, and normocalcemia." (PMID 29692810, 2018). "Secondary hyperparathyroidism (SHPT), characterized by the elevation of serum parathyroid hormone (PTH) levels, is a common disorder in patients with chronic kidney disease (CKD), especially those on renal replacement therapy." (PMID 29614098, 2018). "In conclusion, all of the reported indirect effects of energy-dense diets on PTH point towards an increase in PTH, which would be counterproductive in CKD patients with secondary hyperparathyroidism." (PMID 30513703, 2018). "In their cases, the preoperative PTH level in VDD group was significant higher than that of control group (mean: 60.35 vs. 22.4 pg/mL, P = 0.0001), which suggested the presence of secondary hyperparathyroidism." (PMID 29100453, 2017). "At baseline, 37 (21.1%) participants showed parathyroid hormone (PTH) concentrations above the upper limit of the reference range (i.e., 65.0 pg/mL), suggesting secondary hyperparathyroidism." (PMID 28629132, 2017). "These higher than normal levels of PTH in cKO mice suggest the involvement of multiple factors, other than FGF23/αKlotho/FGFR signalling, in the pathogenesis of secondary hyperparathyroidism." (PMID 28094278, 2017). "Secondary hyperparathyroidism (SHPT) is widely prevalent in patients with chronic renal failure (CRF), characterized by parathyroid hyperplasia and elevated parathyroid hormone (PTH)." (PMID 27034943, 2016). "Although disrupted phosphate homeostasis in patients with CKD also induces secondary hyperparathyroidism, the elevation of serum FGF-23 occurs earlier than that of serum PTH levels." (PMID 26186634, 2015). "These PTH levels confirmed the presence of PTX in the PTX+CKD group (lowest PTH levels) and secondary hyperparathyroidism in the CKD group (highest PTH levels)." (PMID 26186634, 2015). "Second, the fact that PTH levels were not measured precluded the ability to determine whether or not the relationship between 25(OH)D3 and clinical measures of adiposity was caused by secondary hyperparathyroidism." (PMID 24466233, 2014). "In face of our results, 5/6 Nx model should be employed to study the effects of intervention on blood pressure, on kidney disease progression, on serum levels of PTH, FGF-23 and calcitriol or on mild bone lesions of secondary hyperparathyroidism." (PMID 24885705, 2014). "Dialysis patients with severe secondary hyperparathyroidism who underwent parathyroidectomy showed a decrease in FGF23, and FGF23 levels correlated positively with PTH levels in these patients." (PMID 24625659, 2014). "In high-turnover bone disease, e.g., secondary hyperparathyroidism in CKD patients, PTH can be controlled by many drugs, including phosphate binders, vitamin D, and cinacalcet." (PMID 24289746, 2013).
secondary hyperparathyroidism (continued). "All hypercalcemic patients demonstrated suppressed PTH (6.2±2.0 pg/mL, range 3.3-9.6 pg/mL; reference range 10-65 pg/mL), confirming a non-parathyroid-mediated mechanism and excluding primary/secondary hyperparathyroidism." (PMID 41658645, 2026). "Because secondary hyperparathyroidism (SHPT) was considered the most likely cause in a dialysis patient, her medications were adjusted, but her PTH levels did not improve, and she was referred to our department." (PMID 41216108, 2025). "The secondary hyperparathyroidism (SHPT) in chronic kidney disease (CKD), characterized by elevated parathyroid hormone (PTH), parathyroid gland overgrowth, and disordered mineral metabolism, is a major contributor to the high rates of bone disease and cardiovascular mortality in CKD patients." (PMID 41515987, 2025). "Furthermore, intact PTH levels reflect bone histology in patients undergoing HD24, and such secondary hyperparathyroidism would lead to increased bone resorption and formation." (PMID 39748056, 2025). "Although VitD3 supplements decreased PTH levels by 34% in patient #1, patients #2 and #3 experienced only clinically insignificant 3% to 5% increases in PTH after VitD3 supplementation—indicating the absence of secondary hyperparathyroidism at baseline." (PMID 38947416, 2024). "Patient #1 exhibited secondary hyperparathyroidism; VitD3 supplementation decreased parathyroid hormone (PTH) by 34% without a clinically significant change in PTH levels in the other 2 individuals." (PMID 38947416, 2024). "Another consequence of low vitamin D levels is an excess secretion of PTH, leading to secondary hyperparathyroidism which further increases osteoid surface and volume, but not overall thickness causing a broadening." (PMID 39301310, 2024). "In the case of calcimimetics for treatment of secondary hyperparathyroidism, biochemical effects of PTH suppression did not translate into improvements in all-cause or cardiovascular mortality." (PMID 39119524, 2024). "However, the results of our multivariable analysis revealed that the association between serum 1,25(OH)2D levels and LVH/LVDD was independent of blood pressure and intact PTH levels, suggesting that this association might be independent of hypertension and secondary hyperparathyroidism." (PMID 38722953, 2024). "The increase in PTH in response to elevated creatinine and urea levels compensates for the calcium-phosphorus imbalance due to impaired kidney function in CKD, where mineral metabolism disruptions can result in secondary hyperparathyroidism." (PMID 39484207, 2024). "Second, the PTH serum levels were extremely high, which usually does not occur in secondary hyperparathyroidism." (PMID 39463573, 2024). "Complex disturbances to mineral metabolism and dysregulation of homeostasis are associated with declining kidney function in CKD, and a frequent complication is secondary hyperparathyroidism (SHPT), defined by elevated serum parathyroid hormone (PTH) and enlargement of the parathyroid glands." (PMID 37834950, 2023). "The current consensus for PTH values in dialyzed patients, with or without medical treatment for secondary hyperparathyroidism is that it should be maintained between 2x-9x times higher than the reference range (usually accepted at 130-600pg/ml)." (PMID 38075043, 2023). "In fact, multifactorial hyporesponsiveness to PTH is a well-documented consequence of CKD and a certain degree of secondary hyperparathyroidism is beneficial in CKD patients, not only because of the positive PTH phosphaturic effect but also in order to maintain a normal bone formation rate." (PMID 37342799, 2023). "In patients with serum 25(OH)D levels >= 30 ng/mL and serum Ca, P, and parathyroid hormone in the normal range, there is no need to start therapy for secondary hyperparathyroidism." (PMID 34626363, 2022).
secondary hyperparathyroidism (continued). "A difference in PTH was found between these two groups (p < 0.05); no patient with secondary hyperparathyroidism was present in the study." (PMID 35267956, 2022). "Because secondary hyperparathyroidism from CKD could affect dental health, we also measured PTH levels." (PMID 36013449, 2022). "Secondary hyperparathyroidism (SHPT), a common complication of end-stage renal disease (ESRD), results from abnormal changes affecting calcium homeostasis and presents with the increased secretion of parathyroid hormone (PTH)." (PMID 36142295, 2022). "Elevated blood phosphorus can lead to increased levels of PTH and FGF23, the latter being a major regulator of serum phosphorus synthesized and released by osteoblasts, which plays a role in the metabolism of vitamin D and secondary hyperparathyroidism." (PMID 33928079, 2021). "Perhaps, the non-suppressed PTH can be at leastpartially explained by the occurrence of secondary hyperparathyroidism." (PMID 32779690, 2021). "The mechanisms leading to secondary hyperparathyroidism in CKD include not only the reduction in functional kidney mass and FGF23-induced suppression of vitamin D hormone synthesis, but also skeletal resistance to PTH." (PMID 34290280, 2021). "Nevertheless, a negative feedback effect of PTH on leptin secretion was proposed in case of secondary hyperparathyroidism." (PMID 34422722, 2021). "Chronic kidney disease (CKD) may involve secondary hyperparathyroidism (SHPT) characterized mainly by abnormal metabolism of calcium and phosphate, and increased production and secretion of parathyroid hormone (PTH)." (PMID 32236781, 2020). "None of the participants had secondary hyperparathyroidism (PTH > 6.9 pmol/l), but 20% (23% of cases vs. 17% of controls) had PTH levels below lower limits of the reference interval." (PMID 33052935, 2020). "Both low plasma 1.25 dihydroxyvitamin D and low calcium may finally explain why plasma PTH tended to increase after FCM, which is in line with secondary hyperparathyroidism reported after FCM in other trials." (PMID 32654663, 2020). "Several studies have shown that the increase in the PTH level may be caused by a decrease in serum Ca2+ rather than a direct effect of aldosterone in patients with PA, as a low Ca2+ level may contribute to secondary hyperparathyroidism and eventually affect bone mass and strength." (PMID 32973674, 2020). "Secondary hyperparathyroidism (sHPT), a complication of chronic kidney disease (CKD) characterized by persistently elevated parathyroid hormone (PTH), alterations in calcium-phosphorus homeostasis, and vitamin D metabolism, affects 50% of children receiving dialysis." (PMID 32367309, 2020). "In elderly non-dialysis CKD patients with secondary hyperparathyroidism, we suggest lowering parathyroid hormone levels within the normal range by treating abnormalities in serum phosphate and calcium levels before administering active vitamin D agents." (PMID 30506489, 2019). "Patrick T. Rhino did not demonstrate any apparent signs of primary or secondary hyperparathyroidism, and his pre-mortem serum creatinine, PTH, calcium and alkaline phosphatase levels were normal." (PMID 29124354, 2018). "Secondary hyperparathyroidism is a response to low calcium levels related to hypovitaminosis D. It is well established that there is an inverse relationship between serum 25-hydroxyvitamin D (25-OHD) and serum PTH." (PMID 30723655, 2018). "Calcitriol suppresses the release of parathyroid hormone (PTH); however, in CKD this mechanism is blunted due to decreased production of calcitriol, leading to over-release of parathyroid hormone in a condition called secondary hyperparathyroidism." (PMID 28287463, 2017). "Nevertheless, the presence of secondary hyperparathyroidism among bariatric patients is still a matter of debate since some investigators reported normal levels of PTH, while others did not." (PMID 28724055, 2017).
secondary hyperparathyroidism (continued). "Although cholecalciferol supplementation did not seem to correct the secondary hyperparathyroidism in the qualitative analysis it had an effect over PTH concentration so for each increasing unit of vitamin D, PTH decreased 0.213 pg/mL (p < 0.001)." (PMID 27699068, 2016). "In the present study, the inverse association between PTH and serum hemoglobin concentration was observed across the whole spectrum of non-dialysis CKD without severe secondary hyperparathyroidism." (PMID 25113067, 2015). "Consistently elevated PTH levels necessitated parathyroid scintigraphy to rule out secondary hyperparathyroidism, which turned out to be normal." (PMID 26132292, 2015). "In this study we evaluated the association between PTH and hemoglobin in CKD-patients without severe secondary hyperparathyroidism." (PMID 25113067, 2015). "Secondary hyperparathyroidism (SHPT) among patients with chronic kidney disease (CKD) results from decreased active vitamin D and is manifested by low serum calcium and elevated levels of phosphorus and parathyroid hormone (PTH)." (PMID 26510587, 2015). "In a recently published study, secondary hyperparathyroidism was reported in three fourths of infants with VLBW who had radiological evidence of osteopenia and it was suggested that PTH could be a marker of bone demineralization in the newborn." (PMID 24932605, 2014). "The effects of pre-transplantation medication for secondary hyperparathyroidism on post-transplantation parathyroid hormone (PTH) and calcium levels have not yet been conclusively determined." (PMID 25606342, 2014). "Secondary hyperparathyroidism (SHPT) is a common complication of chronic kidney disease (CKD) and is characterized by abnormalities in serum calcium, serum phosphate, parathyroid hormone (PTH) concentrations, vitamin D metabolism, and bone turnover." (PMID 22742720, 2012). "Brown tumor is mainly due to secondary hyperparathyroidism in patients with renal insufficiency, but it has also been described as an extremely rare manifestation of PHPT, usually resulting from PTH overproduction by adenomas or carcinomas of the parathyroid glands." (PMID 22204520, 2011). "Similarly, in patients with chronic kidney disease and secondary hyperparathyroidism, correction of aminoaciduria correlated with vitamin D replacement rather than changes in PTH." (PMID 41142409, 2025). "Of note, in our study, calcium serum levels in the p-PPI group did not decrease over the 2-year study period and were accompanied by a small increase in PTH serum levels (within the normal limits of PTH reference ranges), and thus not suggestive of secondary hyperparathyroidism." (PMID 41125947, 2025). "Reported that in clinical trials for pediatric patients with secondary hyperparathyroidism (SHPT) undergoing hemodialysis, 7.4–57.1% of subjects treated with cinacalcet achieved PTH levels within the recommended target range, while 22.2–70.6% experienced a PTH reduction of ≥30%." (PMID 40837352, 2025). "Also, in a study that was aimed to determine the effect of propofol on intraoperative blood levels of PTH testing, the researchers performed a clinical trial on patients with secondary hyperparathyroidism who underwent a nonparathyroid operation." (PMID 35685611, 2022). "The levels of 25(OH)-vitamin D and similar PTH in diabetic-obese and non-diabetic-obese women lead us to conclude that in our study the hypovitaminosis D and secondary hyperparathyroidism that our patients with T2DM present are determined for associated obesity." (PMID 35789433, 2022). "Although there is no consensus on the optimal serum 25(OH)D concentration or parathyroid hormone targets in patients with secondary hyperparathyroidism, recent evidence suggests that 25(OH)D levels > 50 ng/mL are required to effectively reduce parathyroid hormone levels." (PMID 34626363, 2022).